PLA2G4A (phospholipase A2 group IVA)
Diseases named in the same sentence as PLA2G4A in open-access papers (continued):
Sharing a sentence is not in itself a finding about the gene and the disease.
schizophrenia (4 papers, 2016 to 2024). A major psychotic disorder characterized by abnormalities in the perception or expression of reality. "Single nucleotide polymorphisms (SNPs) in the PLA2G4A have been demonstrated in several studies to potentially significantly correlate with the susceptibility to schizophrenia and its clinical symptoms." (PMID 38816399, 2024). "We screened and validated that the deletion of the PLA2G4A gene from the PLA2 superfamily was significantly associated with susceptibility to schizophrenia." (PMID 38816399, 2024). "The relationship between the deletion of PLA2G4A and susceptibility to schizophrenia was then reaffirmed in the validation group of 806 individuals." (PMID 38816399, 2024). "One schizophrenia patient from the SRA dataset was identified to carry complete deletion of PLA2G4A gene, which was classified as “pathogenic”." (PMID 38816399, 2024). "The BanI polymorphism located in the 5’UTR region of the PLA2G4A gene has undergone repeated validation, demonstrating a substantial correlation with the susceptibility to schizophrenia and clinical characteristics." (PMID 38816399, 2024). "Moreover, the analysis results in different genders indicate that the deletion of the PLA2G4A gene significantly increased the risk of schizophrenia in both males and females." (PMID 38816399, 2024). "This suggested that copy number variants in PLA2G4A may be associated with susceptibility to schizophrenia." (PMID 38816399, 2024). "This study suggests that copy number deletion of the PLA2G4A gene may increase the risk of schizophrenia by reducing the expression levels of cPLA2 enzyme." (PMID 38816399, 2024). "Genetic studies suggested that the PLA2G4A gene, coding for a cytosolic form of PLA2, may be associated with schizophrenia, although failure to replicate the PLA2G4A SNP association results has been reported." (PMID 27434078, 2016). "Finally, the detailed exploration and validation of how the deletion of the PLA2G4A gene copy number influences the risk of schizophrenia should be carried out using cellular or animal models, to establish a foundation for genetic variant screening and targeted therapies for schizophrenia." (PMID 38816399, 2024). "This study indicated that in the discovery stage, an increased copy number of PLA2G6 and the deletion of PLA2G3, PLA2G4A, PLA2G4F and PLA2G12F was associated with increased risk of schizophrenia." (PMID 38816399, 2024). "We employed Chi-squared test and Fisher’s exact test to examine the associations between the genotype of PLA2G4A CNV and 29 clinical schizophrenia phenotypes." (PMID 38816399, 2024). "Among female patients, there were significant differences in the symptoms of erotomanic delusion (p = 0.034) between schizophrenia cases with PLA2G4A deletion CNV and those with other genotypes." (PMID 38816399, 2024). "For instance, SNP rs1549637 in PLA2G4C, BanI SNP in the PLA2G4A locus, and SNP rs1648833 in PLA2G4B may contribute to the risk of schizophrenia." (PMID 27434078, 2016). "In summary, this study suggested that the functional copy number deletion in the PLA2G4A gene could affect the risk of schizophrenia and clinical phenotypes by reducing the expression of cytosolic PLA2, which may be an indicator of susceptibility to schizophrenia." (PMID 38816399, 2024). "We identified a copy number variation segment in a schizophrenia patient involving a concurrent deletion of the PTGS2 and PLA2G4A genes." (PMID 38816399, 2024).
atherosclerosis (3 papers, 2022 to 2025). A disease characterized by the build-up of fatty material and calcium deposition in the arterial wall resulting in partial or complete occlusion of the arterial lumen. "Our goal was to determine whether genetic variability in three candidate phospholipase-related genes, namely PLA2G7, SCARB1 and PLA2G4A, was associated with atherosclerosis and the occurrence of CV events in a population of nephrosclerosis patients." (PMID 35586043, 2022). "PLA2G4A and PLA2G7 harboured several SNPs associated with atherosclerosis measurements in the patients, namely common carotid intima media thickness (ccIMT), presence of plaques, number of plaques detected and 2-years ccIMT progression (significant p-values ranging from 0.0004 to 0.047)." (PMID 35586043, 2022). "Whilst there is no available information on the effect of PLA2G4A variants on atherosclerosis measurements, there are some previous reports linking PLA2G7 SNPs to this pathology." (PMID 35586043, 2022). "On the other hand, while searching for a set of genes associated with the MAPK signaling pathway, we found a group of four DEG members of this pathway: PLA2G4A, IL1A, RASGRP3, and DDIT3, which are molecules related to inflammation, apoptosis, signal transduction, and atherosclerosis." (PMID 40332370, 2025).
coronary artery disease (3 papers, 2021 to 2024). "PLA2G4A rs1015710 is associated with ischemic heart disease (P = 0.013)." (PMID 38935682, 2024). "Moreover, polymorphisms in PLA2G4A have also been related to myocardial infarction and coronary artery disease." (PMID 35586043, 2022).
leukemia (3 papers, 2021 to 2022). A malignant (clonal) hematologic disorder, involving hematopoietic stem cells and characterized by the presence of primitive or atypical myeloid or lymphoid cells in the bone marrow and the blood. "As we identified an evident decrease of NKT cells in the high-risk TME, we examined the effect of PLA2G4A inhibition on NK-mediated cytotoxicity against leukemia cells." (PMID 36338749, 2022). "Pharmaceutical targeting of PLA2G4A increased the expression of NKG2DL in leukemia cells in vitro and thus enhanced the NK cell-mediated immunosurveillance." (PMID 36338749, 2022). "Pharmaceutically inhibiting the FAM enzyme PLA2G4A increased expressions of NKG2D ligands in leukemia cells, thus enhancing NK cell-mediated cytotoxicity against leukemia cells." (PMID 36338749, 2022). "More importantly, pharmaceutically targeting the FAM gene PLA2G4A enhanced the NK cell-mediated immunosurveillance by increasing NKG2D ligand expression in leukemia cells." (PMID 36338749, 2022). "This approach led to the identification of PLA2G4A as a potential target and prognostic marker for H9M-driven leukemia." (PMID 34502319, 2021). "Since the importance of PGE2-mediated induction of β-catenin for the formation and maintenance of LSC was initially discovered through upregulation of Ptger and Ptgs1 in murine leukemia, we subsequently focused on the investigation of Pla2g4a as a leukemia essential gene." (PMID 34502319, 2021). "More importantly, we demonstrated that FAM inhibition via pharmaceutical targeting of PLA2G4A, a highly expressed FAM gene in AML patients with poor prognosis, enhanced the NK cell-mediated immunosurveillance in leukemia cells." (PMID 36338749, 2022). "Thus, we treated leukemia cell lines THP1, U937, and HL60 with PLA2G4A inhibitor AACOCF3, an analog of arachidonic acid that inhibits the PLA2G4A phospholipase activity by competing for the active catalytic site." (PMID 36338749, 2022).
melanoma (3 papers, 2018 to 2022). A malignant, usually aggressive tumor composed of atypical, neoplastic melanocytes. "On the other hand, the top downregulated genes formed 4 subgroups and were related to melanogenesis (Wnt5a, Mitf, Pomc, Mc1r, Kit), melanoma (Fgf9, Fgf12, Fgf2), MAPK signaling pathway (Ncam1, Prkcb, Map3k4, Pla2g4a, Mapk14, Mapk11), and aging (Tgfbr1, Il6, Nox4)." (PMID 36555664, 2022).
ovarian carcinoma (3 papers, 2014 to 2024). A malignant neoplasm originating from the surface ovarian epithelium. "PLA2G4A encodes phospholipase A2, and quinacrine may inhibit ovarian cancer by inhibiting PLA2G4A which in turn reduces arachidonic acid metabolites and thus inhibits ovarian cancer development." (PMID 38651149, 2024). "Among them, FNTA, HSPA5, NEU1, CCND1, CASP1, CASP3 had a negative causal association with ovarian cancer development, and HMGCR, PLA2G4A, ITGAL, PTGS1, FNTB had a positive causal association with ovarian cancer development." (PMID 38651149, 2024). "By screening 31 drugs with 110 targets, FNTA, HSPA5, NEU1, CCND1, CASP1, CASP3 were negatively correlated with ovarian cancer, and HMGCR, PLA2G4A, ITGAL, PTGS1, FNTB were positively correlated with ovarian cancer." (PMID 38651149, 2024).
pancreatic cancer (3 papers, 2015 to 2025). "In pancreatic cancer, HDAC5 inhibits the binding of GATA1 to the promoter region of the downstream gene PLA2G4A by deacetylating the transcription factor GATA1." (PMID 40781327, 2025).
virus infection (3 papers, 2012 to 2024). "PLA2G4A specifically has not been linked directly to virus infection; however, cytosolic phospholipases have been associated with biogenesis and membrane remodeling of West Nile virus." (PMID 38953667, 2024). "Finally, inhibitors of the PLA2G4A which have been pursued and brought into clinical development for treating inflammatory diseases may prove useful as antiviral therapeutics for the treatment of chronic HCV infection and possibly other viral diseases." (PMID 22911431, 2012).
brain trauma (2 papers, 2021 to 2022). "Sarkar C and others found that autophagy of TBI may have other pathways, such as PLA2G4A/cPLA2-mediated lysosomal membrane damage leading to inhibition of autophagy and neurodegeneration after brain trauma." (PMID 33819197, 2021).
cystic fibrosis (2 papers, 2005 to 2012). Autosomal recessive disorder caused by pathogenic variants in the CFTR gene (cystic fibrosis transmembrane conductance regulator), which encodes a chloride and bicarbonate channel expressed in epithelial cells, and follow the diagnosis criteria. "Both SERPINB4 and CTSC are up-regulated in IL13 treated human primary bronchial epithelial cells on air liquid interface culture, and PLA2G4A is more active in bronchial explants from individuals with cystic fibrosis." (PMID 22676183, 2012).
diabetes (2 papers, 2022 to 2024). "Acupuncture also upregulates PLA2G4A and downregulates miR-32-3p, potentially enhancing ovulation and improving endocrine function, especially in PCOS patients with diabetes." (PMID 39655237, 2024).
endometriosis (2 papers, 2020 to 2025). The growth of functional endometrial tissue in anatomic sites outside the uterine body. "There has been limited research on the roles of ACSL5, PLA2G4A, EHHADH, GPAM, PLA2G15, SULT2A1, and ACSL3 in endometriosis, highlighting the necessity for further investigation to elucidate their contributions to its pathogenesis." (PMID 40527850, 2025).
ischemia (2 papers, 2009 to 2022). A hypoperfusion of the BLOOD through an organ or tissue caused by a PATHOLOGIC CONSTRICTION or obstruction of its BLOOD VESSELS, or an absence of BLOOD CIRCULATION. "In this study, we found that ischemia-induced neuronal PTRF expression could lead to autophagy, lipid peroxidation, and ferroptosis via PLA2G4A after cerebral I/R injury." (PMID 35547748, 2022).
multiple myeloma (2 papers, 2021 to 2023). "We found higher expression of PLA2G4A in multiple myeloma patients, as well as patients with the asymptomatic premalignant stage of multiple myeloma known as MGUS, in comparison to healthy individuals." (PMID 34946532, 2021). "There was approximately a 3-fold increase in PLA2G4A gene expression in multiple myeloma and a 2.3-fold increase in MGUS patient samples." (PMID 34946532, 2021). "Overexpression of the PLA2G4A gene in multiple myeloma cell lines, and samples from patients with either symptomatic or asymptomatic myeloma, led us further to investigate the role of cPLA2α in multiple myeloma using MM cell lines as models." (PMID 34946532, 2021). "Moreover, high gene expression of PLA2G4A has been correlated with poor patient outcomes, e.g., relapse, development of metastasis and lower survival, in cancers of lung, liver, and breast, glioblastoma, and multiple myeloma." (PMID 34946532, 2021). "Multiple myeloma (MM) represented hematological cancer that overexpressed PLA2G4A, and we showed that two cPLA2α inhibitors, AVX420 and AVX002, reduced viability in different multiple myeloma cell lines, likely via induction of apoptosis." (PMID 34946532, 2021).
non-small cell lung carcinoma (2 papers, 2016 to 2020). A group of at least three distinct histological types of lung cancer, including non-small cell squamous cell carcinoma, adenocarcinoma, and large cell carcinoma. "Inhibition of COX2/PGE2 pathway can effectively suppress tumor growth, EMT and metastasis of non small cell lung cancer or extrahepatic cholangiocarcinoma through PLA2G4A/PGE2/STAT3 pathway." (PMID 32546278, 2020).
urothelial carcinoma (2 papers, 2012 to 2016). A malignant neoplasm derived from the transitional epithelium of the urinary tract (urinary bladder, ureter, urethra, or renal pelvis). "This is in accordance with our observation that in the majority of patients with urothelial carcinoma PLA2G4A is downregulated in the tumor." (PMID 23145155, 2012). "However, they found one full-length HERV-E element, located in the antisense direction in an intron of the PLA2G4A gene that is transcribed in urothelial carcinoma and appears to modulate PLA2G4A expression, thereby possibly contributing to carcinogenesis, although the mechanism is not clear." (PMID 27980689, 2016). "To compare the data obtained from UROtsa cells with the situation in vivo, we analyzed PLA2G4A and HERV-Ec1-gag transcript levels in DNA-free RNA preparations from additional patients (n = 11) with urothelial carcinoma." (PMID 23145155, 2012). "PLA2G4A and HERV-Ec1 displayed reciprocal transcript levels in 7 of 11 urothelial carcinoma patients." (PMID 23145155, 2012). "Furthermore, a HERV-E-related provirus (HERV-Ec1) transcribed in urothelial carcinoma and non-malignant urothelial tissue was identified that is located in antisense orientation in an intron of the PLA2G4A gene." (PMID 23145155, 2012).
acne vulgaris (1 paper, 2024). "The biological annotation analysis indicates that we have identified 3 pairs of associated genes between gut microbiota and acne vulgaris, including PLA2G4A/FADS2, TIMP3/ADAMTS9 and ZC3H3/CPSF4L." (PMID 38371936, 2024). "After conducting biological annotation, we identified six genes (PLA2G4A, FADS2, TIMP17, ADAMTS9, ZC3H3, and CPSF4L) that may be associated with the pathogenic gut microbiota of acne vulgaris patients." (PMID 38371936, 2024). "In particular, the fatty acid metabolism pathway shows enrichment of PLA2G4A/FADS2, which further supports the correlation between four gut microbes and acne vulgaris." (PMID 38371936, 2024).
adenoma (1 paper, 2023). A neoplasm arising from the epithelium. "Enhanced expression of Pla2g4a was detected in the adenomas of ApcMin/+ mice (an animal model of FAP) vs. normal mucosa of WT mice, accompanied by the overexpression of the inflammatory cytokine IL-6." (PMID 37173923, 2023).
Arthritis (1 paper, 2013). Inflammation of a joint. "Moreover, PC downregulated the expression of PLA2G4A (−1.61-fold change), PLAUR (−1.94-fold change), and MMP9 (−1.91-fold change), all of which have been previously implicated in the pathogenesis of arthritis." (PMID 23936839, 2013).
breast tumor (1 paper, 2022). "We observed a significant positive correlation between S100A7 and PLA2G4A in distinct signal transduction pathways (r = 0.93) and among different breast tumor samples from pre-and post-chemotherapy (r = 0.59)." (PMID 35135586, 2022). "In agreement with our previous results, we observed that S100A7 and PLA2G4A revealed significantly higher expression in high-grade tumors compared to low-grade breast tumor tissues." (PMID 35135586, 2022).
cardioembolic stroke (1 paper, 2024). "The risk variants rs528002287 (locus 15q26.3) in PCSK6 and rs148010464 (locus 1q31.1) an intergenic variant in PLA2G4A/LINC01036 for stroke were unique to South Asia, and were found to be associated with cardioembolic stroke and small vessel stroke in South Asians." (PMID 39268810, 2024).
childhood asthma (1 paper, 2023). "The PLA2G4A gene has been shown to be associated with childhood asthma." (PMID 37060021, 2023).
enteropathy (1 paper, 2015). "This enteropathy has been shown to be an autosomal recessive inherited disease caused by mutations in the PLA2G4A gene." (PMID 26539716, 2015).
gout (1 paper, 2021). A condition characterized by painful swelling of the joints, which is caused by deposition of urate crystals. "Interestingly, the MDT score of 5 compounds (D1-D5) on PLA2G4A demonstrated invalid affinity scores (>−6.0 kcal*mol−1); accordingly, we did not regard them as potential bioactives against gout." (PMID 34502281, 2021).
Hepatitis (1 paper, 2023). Inflammation of the liver. "In HBV-induced hepatitis, the expressions of MAPK1, PTGS1, PTGS2, PLA2G4A, and TLR4 increased significantly." (PMID 37741847, 2023).
insomnia (1 paper, 2024). A sleep disorder characterized by difficulty in falling asleep and/or remaining asleep. "In insomnia patients, PLA2G4A was reported to be upregulated by 1.88-fold after improvement in sleep." (PMID 39268810, 2024).
intrahepatic cholangiocarcinoma (1 paper, 2020). A carcinoma that arises from the intrahepatic bile duct epithelium in any site of the intrahepatic biliary tree. "Previous study has identified it as a prognostic biomarker of perihilar and distal cholangiocarcinoma but not intrahepatic cholangiocarcinoma, the gene promotes extrahepatic cholangiocarcinoma metastasis by facilitating the epithelial-mesenchymal transition via the PLA2G4A/PGE2/STAT3 pathway." (PMID 32514252, 2020).
ischemic stroke (1 paper, 2022). A stroke disorder caused by obstruction of blood flow to the brain, due to thrombotic (local blood clot formation) or embolic (due to a blood clot or other material traveling from another site) event. "Importantly, both activity and expression levels of PLA2G4A were increased in neurodegenerative diseases, traumatic brain injury (TBI) and ischemic stroke, and implicated in neuronal cell death 21, making it an attractive target for therapeutic intervention." (PMID 35547748, 2022).
myelodysplastic syndrome (1 paper, 2023). A clonal hematopoietic disorder characterized by dysplasia and ineffective hematopoiesis in one or more of the hematopoietic cell lines. "Higher PLA2G4A expression results in worse OS and mutations in NRAS, which are known to contribute to the development of myelodysplastic syndrome development." (PMID 38022627, 2023).
myocardial ischemia (1 paper, 2022). A disorder of cardiac function caused by insufficient blood flow to the muscle tissue of the heart. "Based on the results of network pharmacology analysis, first, the top four genes (PRKCA/MAPK3/PRKCG/PLA2G4A) and PRKCE (an isoform of the large PKC family) were picked up for validation in the animal model of surgery-induced myocardial ischemia." (PMID 35141226, 2022).